CCR2 (C-C motif chemokine receptor 2)
Diseases named in the same sentence as CCR2 in open-access papers (continued):
Sharing a sentence is not in itself a finding about the gene and the disease.
Sepsis (continued). "Using a murine model of polymicrobial sepsis in pregnancy, C-C chemokine receptor type 2 (CCR2), which is a monocyte chemoattractant receptor, knockout mice have reduced inflammatory cell trafficking, but increased bacteraemia and worse survival." (PMID 31671794, 2019). "Since macrophages with altered expression levels of TNFα, CCR2 and iNOS are expected to affect lung inflammation, homeostasis and host resistance, we determined the functional implication of NFATc3 deletion on sepsis-induced ALI in mouse CLP sepsis models." (PMID 29535830, 2018). "Inappropriate infiltration of neutrophils resulted in the remote organ dysfunction in sepsis, which was further identified as C-C chemokine receptor type 2 (CCR2) dependent." (PMID 29326712, 2017). "Sepsis also resulted in infiltration of monocytes and neutrophils into the CNS at least two weeks after sepsis in a CCR2 independent manner." (PMID 26862765, 2016). "It was demonstrated that CCR2 is induced on the neutrophil surface in mice and patients with sepsis in a TLR2- or TLR4-dependent manner." (PMID 27199981, 2016). "Due to the dual role of NE on CCR2 expression in macrophages, caution should be taken when targeting CCR2 in sepsis." (PMID 23844252, 2013). "Our results not only provide greater insight towards understanding the pathophysiology of severe burn and sepsis, but also raise some concerns regarding immunotherapies targeting CCR2 in septic patients." (PMID 23844252, 2013). "The discrepancy in the findings of these two studies may be partially explained by the less explored role of CCR2 in controlling Gr-1+ neutrophil migration during sepsis or models of acute inflammation." (PMID 34663098, 2021). "The authors conclude that CCR2 may help drive the inappropriate infiltration of neutrophils into remote organs during sepsis." (PMID 30931316, 2019). "Interestingly, the altered expression patterns and functions of CXCR2 and CCR2 seen during sepsis are driven by TLR activation in neutrophils." (PMID 30931316, 2019). "Comparison of LPS stimulated NFATc3−/− and WT BMDM gene expression indicated distinct down regulation of LPS induced CCR2 and TNFα in NFATc3−/− macrophages, suggesting that NFATc3 regulates macrophage gene expression thereby regulates pathogenesis of sepsis induced-ALI." (PMID 29535830, 2018). "Since blocking of CCR2 has already proven protective in a severe sepsis model, it might be a promising candidate to prevent sepsis-induced immunosuppression." (PMID 29218051, 2017). "Moreover, CCR2 expression is positively correlated with the severity of the disease, as measured using the Sepsis-related Organ Failure Assessment (SOFA) score." (PMID 27199981, 2016). "This chemokine receptor pathway may be an attractive therapeutic approach for wound healing, however the specific role played by CCR2 on macrophage in severe burn and sepsis is yet to be examined." (PMID 23844252, 2013). "Another study found that CCR2 was important for neutrophil tissue infiltration during sepsis." (PMID 23844252, 2013). "A recent report found that CCR2 is essential for neutrophil infiltration during sepsis and suggested that targeting CCR2 might be a novel immunotherapy for sepsis." (PMID 23844252, 2013). "Our data suggest that NE may regulate tissue immune response by regulating CCR2-dependent monocyte tissue infiltration in severe burn and sepsis." (PMID 23844252, 2013). "Indeed, in mouse serum, mouse CCR2 protein (the receptor for CCL2) is necessary for expression of mouse IL6 protein that is increased by experimentally induced sepsis in mouse, and IL1 protein increases expression of CCL2 protein." (PMID 21906276, 2011). "Inhibit the expression of MDSC CCR2 and CXCR2 to suppress the aggregation of MDSCs and improve the survival rates of sepsis mice." (PMID 40153575, 2025).
Sepsis (continued). "The study elucidates the critical role of protective immune cell phenotypes, such as CCR2 + CD14 − CD16 + monocytes and HLA-DR + NK cells, in modulating sepsis progression through coordinated innate and adaptive immune responses." (PMID 40797460, 2025). "Under sepsis-like conditions, CRM (CCR2- and CCR2+) undergo local expansion and protect against cardiomyocytes death." (PMID 36926341, 2023). "In the mouse model of sepsis, IMD decreases inflammatory conditions via downregulating CCR2 expression." (PMID 34434487, 2021). "CCR2, the receptor for MCP-1 (CCL2) has also been found up-regulated in macrophages in lungs from patients with sepsis-induced lung injury." (PMID 32154187, 2020). "MFI of CD64, CCR2, and CXCR2 surface receptors stratified by sepsis status† (n = 30: septic shock = 19, infection = 11)." (PMID 33424860, 2020). "Multilevel mixed model analysis examining the longitudinal correlations between the percentages of CD64-positive neutrophils, CCR2-positive neutrophils, CXCR2-negative neutrophils, apoptotic, and NETosis and sepsis status† (n = 30)." (PMID 33424860, 2020). "CXCR2 surface level is related to sepsis activity while CD64 and CCR2 surface levels link to sepsis via infection." (PMID 33424860, 2020). "We have reported a pivotal role for Nuclear Factors of Activated T cells (NFATc3) in regulating macrophage phenotype during sepsis induced ALI and subsequent studies demonstrate that NFATc3 transcriptionally regulates macrophage CCR2 and TNFα gene expression." (PMID 29535830, 2018). "The CCR2 and S100A11 genes are up-regulated in early stages of sepsis in blood but down-regulated in the peritoneal cells in our sepsis model." (PMID 23009705, 2012). "Sepsis is one of the well-established diseases resulting in specific patterns of neutrophil dysfunctions; increased CD64 and CCR2 surface levels; decreased CXCR2 surface level; apoptosis delay; and increased NETosis are widely-cited sepsis-related neutrophil dysfunctions." (PMID 33424860, 2020). "In contrast to our findings on CXCR2 surface level, our study fails to demonstrate the changes of CD64 and CCR2 surface levels as sepsis-related." (PMID 33424860, 2020). "The immunoreactivity of both molecules was tested on lung samples obtained from 8 non-sepsis control cases and 9 sepsis cases: both CCR2+ and CX3CR1+ mononuclear cells were significantly higher in the sepsis group compared to controls (p < 0.01)." (PMID 33092081, 2020). "While CCR2 is usually not considered a key receptor for neutrophil recruitment, previous studies show it is important for neutrophil chemotaxis during sepsis." (PMID 32391790, 2020). "CD64 surface level, CCR2 surface level, and NETosis are not directly sepsis-related; their relationship with sepsis is instead mediated by the effect of infection." (PMID 33424860, 2020). "Furthermore, it was recently reported that mice lacking Ccr2 had decreased myeloid cell infiltration into the brain and attenuated cognitive impairment during a model of sepsis induced by Streptococcus pneumoniae injection into the lungs." (PMID 32391790, 2020). "Thus, the accumulation of CD4+ DCs in the bone marrow during sepsis is regulated by CCR2 but seems to be independent of monocyte mobilization." (PMID 29218051, 2017). "The daily percentages of CD64-positive neutrophils, CCR2-positive neutrophils, CXCR2-negative neutrophils, apoptosis, and NETosis stratified by sepsis status† (n = 30: septic shock = 19, infection = 11)." (PMID 33424860, 2020). "However, the expression level and positive-cell ratio of CCR2 and CCR7 among CD3ε-B220-Gr-1-TER119-CD11c+MHC class II+ cells did not exhibit any sepsis-induced remarkable alteration." (PMID 31323786, 2019).
Alzheimer disease (32 papers, 2012 to 2025). A progressive, neurodegenerative disease characterized by loss of function and death of nerve cells in several areas of the brain leading to loss of cognitive function such as memory and language. "Ccr2-64i and Ccr5 Δ32 Polymorphisms in Patients with Late-Onset Alzheimer’s disease; A Study from Iran (Ccr2-64i And Ccr5 Δ32 Polymorphisms in Alzheimer’s disease)." (PMID 31447666, 2019). "Consistent with this, and in the context of Alzheimer’s disease (AD), a deficiency of CCR2 in a mouse model of AD reduced monocyte trafficking into the CNS, and this was associated with increased Aβ plaque burden and mortality." (PMID 25890218, 2015). "CCR2 expression has also been linked to Alzheimer’s disease or AD." (PMID 40909274, 2025). "Notably, CCR2 deficiency particularly aggravated amyloid β clearance in an Alzheimer’s disease animal model, thereby inducing accelerated deterioration." (PMID 34385589, 2021). "In a model of Alzheimer’s disease, CCR2-/- mice have been found to exhibit impaired microglial recruitment in injured areas, which results in increased mortality." (PMID 27930721, 2016). "Nevertheless, their physiologic role could degenerate into neurotoxic effects during chronic neuroinflammation, as demonstrated in a murine model of Alzheimer’s disease for CCL2/CCR2 and CXCL1/CXCR2." (PMID 40801605, 2025). "CCR2 and its main ligand CCL2 (MCP-1) might also be involved in the altered metabolism of beta-amyloid (Aβ) underlying Alzheimer's disease (AD)." (PMID 22303443, 2012). "Because inflammation may play an important role in progression of Alzheimer’s disease, and CCR2 and CCR5 have a primary function in recruitment of leukocytes to inflammatory sites, we hypothesized that these variations might influence the risk of developing AD in our population." (PMID 23493039, 2012). "In Alzheimer's disease, CD68 (p = 0.026), CD64 (p = 0.002), CHI3L1 (p = 0.016), IL4R (p = 0.005) and CCR2 (p = 0.010) were increased independently of systemic infection." (PMID 30193587, 2018). "While some studies with Alzheimer’s disease mouse models have suggested that CX3CR1 and CCR2 play a role in the progression of disease, we determined that having a single copy of either gene does not alter plaque deposition or microglial CD45 reactivity." (PMID 28923083, 2017). "Ly6Chi /CCR2hi monocyte recruitment into the CNS in models of stroke, peripheral inflammation, Alzheimer’s disease (AD) and EAE are all dependent on CCR2/CCL2 signaling." (PMID 23244217, 2012).
renal fibrosis (31 papers, 2013 to 2025). A final common manifestation of a wide variety of chronic kidney diseases characterized by glomerulosclerosis and tubulointerstitial fibrosis. "CCR2 antagonists demonstrate promise in preclinical models of metabolic dysfunction-associated steatohepatitis and renal fibrosis." (PMID 39748675, 2025). "Blocking this pathway, either through the deletion of Mcp-1 or using a CCR2 antagonist, suppresses renal injury and the associated renal fibrosis." (PMID 38035106, 2023). "These evidences indicate that CCR2 mediate inflammation, and cause collagen accumulation, and promote renal fibrosis, and ultimately cause severe kidney damage." (PMID 35725391, 2022). "Unexpectedly, though, CCR2 deficiency worsened the subsequent renal fibrosis, which was marked by notable intra-renal infiltration of Ly6C− macrophages." (PMID 30926787, 2019). "These Ly6C− macrophages accelerated kidney injury, activated myofibroblasts and in turn exacerbated the ischemia-induced renal fibrosis in both WT and CCR2-deficient mice." (PMID 30926787, 2019). "Our results showed that CCR2 deficiency inhibited renal fibrosis through suppression of myeloid fibroblast infiltration into the kidney." (PMID 24130892, 2013). "Therefore, more attention should be paid to comprehensively investigating the underlying mechanisms of MCP-1/CCR2 axis in renal fibrosis." (PMID 37861543, 2023). "Since CCR2 regulates the accumulation and activation of bone marrow-derived fibroblasts in the kidney in response to obstructive injury, we then examined the effect of CCR2 deficiency on the development of renal fibrosis." (PMID 24130892, 2013). "Histological analysis of the kidneys on day 7 post-AKI revealed the initiation of fibrotic repair, and inhibition of Ccr2 in vivo attenuated the progression of renal fibrosis." (PMID 40953007, 2025). "In the NAFLD model induced by HFD feeding and in db/db mice with renal fibrosis, we observed that CCR2+ macrophages were separated into two groups." (PMID 40995682, 2025). "This indicates that CCR2+PIRB‐ macrophages promote renal fibrosis by enhancing fibroblast proliferation through PDGFB secretion." (PMID 40995682, 2025). "This suggests that CCR2+PIRB+ macrophages are the key immune cells that exacerbate renal fibrosis in patients with NAFLD." (PMID 40995682, 2025). "In several preclinical studies, MCP-1 and CCR2 antagonists, such as mNOX-E36-3’PEG, RS102895, and RS504393, have been successfully used to block the MCP-1/CCR2 axis conduction in treating renal fibrosis." (PMID 37861543, 2023). "Here, we focus on the complex physical processes and general mechanisms of MCP-1/CCR2 axis in renal fibrosis in this review." (PMID 37861543, 2023). "Activation of MCP-1/CCR2 axis can induce chemotaxis and activation of inflammatory cells, and initiate a series of signaling cascades in renal fibrosis." (PMID 37861543, 2023). "More and more scholars show great interest in the MCP-1/CCR2 axis because of its significant participation in renal fibrosis." (PMID 37861543, 2023). "mNOX-E36-3’PEG, an MCP-1 antagonist, can reduce macrophage recruitment to the glomerulus and renal interstitium of diabetic mice by targeting the MCP-1/CCR2 axis and alleviating renal fibrosis in mice with experimental DN." (PMID 37861543, 2023). "The MCP-1/CCR2 axis is important in renal fibrosis, and accumulated experimental evidence provides a good foundation for clinical research." (PMID 37861543, 2023). "In particular we describe the MCP-1/CCR2 axis as a potential target for treating renal fibrosis by using specific examples." (PMID 37861543, 2023). "Activation of the MCP-1/CCR2 axis induces chemotaxis and activation of inflammatory cells and initiates a series of signaling cascades in renal fibrosis." (PMID 38239353, 2023). "It is difficult to achieve significant clinical benefits in the treatment of renal fibrosis by targeting MCP-1 or CCR2 alone." (PMID 37861543, 2023).
renal fibrosis (continued). "Among the chemokines, monocyte chemoattractant protein-1 (MCP-1), also known as C-C motif chemokine ligand 2, together with its main receptor C–C chemokine receptor type 2 (CCR2) are important chemokines in renal fibrosis." (PMID 37861543, 2023). "Chemical or genetic ablation of CCR2 reduces renal fibrosis, TGFβ production, and macrophage accumulation in several models of CKD." (PMID 35806457, 2022). "FACS analysis also indicated that the number of CD11b+CCR2+ monocytes increased in the BM but decreased in the spleen of the RBP-J cKO mice during renal fibrosis." (PMID 29644573, 2019). "Masson Blue and Sirius Red staining for collagen deposition showed aggravation of renal fibrosis in CCR2−/− mice at day 15 after I/R compared to WT mice." (PMID 30926787, 2019). "Masson Blue and Sirius Red staining, and immunofluorescence staining for the expression of α-SMA showed renal fibrosis was alleviated in CCR2−/− mice treated with CLs compared to PBS-treated controls." (PMID 30926787, 2019). "In summary, our data have unveiled that Notch signaling regulates macrophage in renal fibrosis at two levels, namely the CCR2-mediated monocyte recruitment and the local macrophage activation." (PMID 29644573, 2019). "It has been demonstrated that blockading MCP-1 and its receptor CCR-2 pathway reduces renal fibrosis." (PMID 24885946, 2014). "Since bone marrow-derived fibroblasts express the chemokine receptor CCR2, we investigated the role of CCR2 in renal fibrosis using CCR2 knockout (KO) mice." (PMID 24130892, 2013). "Taken together, our results demonstrate that CCR2 signaling plays an important role in the pathogenesis of renal fibrosis through regulation of bone marrow-derived fibroblasts." (PMID 24130892, 2013). "In response to obstructive injury, the activated CCR2 signaling contributes to recruit bone marrow-derived fibroblasts and macrophages into the kidney leading to the development of renal fibrosis." (PMID 24130892, 2013). "A previous report showed that the blockade of the MCP-1 receptor CCR2 can attenuate renal fibrosis in the UUO model." (PMID 23457573, 2013). "Future studies incorporating later-stage AKI datasets and experimental validation at the cellular and molecular levels are needed to confirm whether the co-expression of Ccl6 and Ccr2 directly contributes to renal fibrosis progression." (PMID 40953007, 2025). "Thus, the ANGPTL8/PIRB/ALOX5AP axis is a crucial signaling pathway between the liver and kidneys, and CCR2+PIRB+ macrophages play a pivotal role in the progression of NAFLD‐induced renal fibrosis." (PMID 40995682, 2025). "Results showed that Ccr2 antagonism significantly alleviated renal fibrosis on day 7 post-AKI." (PMID 40953007, 2025). "Among these, only Mmp12 was highly expressed in the Ccl6+Ccr2+Arg1+ population, suggesting that these macrophages may contribute to the progression of renal fibrosis through tissue remodeling mechanisms." (PMID 40953007, 2025). "The known roles of angiotensin 2 receptor type 1 and CCR2 individually in the progression of renal fibrosis, and the synergistic effect of simultaneous receptor inhibition combine to provide a strong therapeutic rationale for the combination approach used in this Phase II trial." (PMID 41426031, 2025). "This discovery challenges the traditional view of homogeneous function among CCR2+ macrophages in renal fibrosis and echoes the emerging evidence of macrophage heterogeneity in metabolic organ interactions (e.g., similar transitions reported in diabetic cardiomyopathy)." (PMID 40995682, 2025). "The MCP-1/CCR2 axis is a potential therapeutic target for renal fibrosis." (PMID 37861543, 2023). "That indicates RS504393 can reduce inflammation and renal fibrosis by targeting MCP-1/CCR2 axis." (PMID 37861543, 2023). "MCP-1/CCR2 axis is an important pathway for chemotactic recruitment of inflammatory cells, and may become a promising therapeutic target for renal fibrosis." (PMID 37861543, 2023).